KRAS (KRas proto-oncogene, GTPase)
Diseases named in the same sentence as KRAS in open-access papers (continued):
Sharing a sentence is not in itself a finding about the gene and the disease.
cancer (continued). "A strong association exists between oncogenic KRAS (G12V) signaling and aberrant DNA methylation, leading to the dysregulation of genes involved in critical cancer-related pathways such as DNA repair, cell cycle progression, and proliferation." (PMID 40275403, 2025). "The p.G12C mutation in KRAS is commonly found in many cancers and was previously untreatable until drugs like sotorasib were developed." (PMID 39842846, 2025). "Curiously, this order correlates with that of their exploitation in cancer, where KRAS is most and HRAS least frequently mutated." (PMID 41248180, 2025). "APC mutations are the most frequently observed mutations, and KRAS mutations are considered major cancer-related genetic mutations." (PMID 41488735, 2025). "BI-2865, a novel pan-KRAS inhibitor, demonstrates activity against a broad spectrum of KRAS mutations—including G12C/D/F/V, G13C/D, and V14I—potentially covering up to 95% of KRAS-driven cancers, thus holding substantial therapeutic promise." (PMID 40980689, 2025). "Nevertheless, there are currently no effective drugs in clinical trials for other mutation sites, underscoring the significance of targeting KRAS-dependent signaling pathways for the treatment of KRAS-mutant cancers." (PMID 39437162, 2025). "The p.G12 mutation is predominant in human cancers harbouring KRAS mutations, with p.G12C being the third most frequently observed." (PMID 39842846, 2025). "There are several reasons why KRAS mutations are ideal therapeutic targets for cancer immunotherapy." (PMID 39846249, 2025). "In this review, we provide a brief overview of KRAS mutations in cancers and tumorigenesis, specifically focusing on currently approved therapies for targeting KRAS, ongoing advances, resistance mechanisms, and novel combinational approaches." (PMID 41309533, 2025). "RBP, as a PPI inhibitor, can overcome drug resistance induced by mutations in cancer cells and can target various types of mutant KRAS." (PMID 40236954, 2025). "Wild strawberry extract is a promising dietary supplement for both wild‐type and KRAS‐mutated patients who exhibit a more aggressive cancer phenotype." (PMID 40207736, 2025). "One of the most common genetic alterations in cancer is the mutation of the KRAS gene (Kirsten rat sarcoma viral oncogene homolog), a member of the RAS gene family." (PMID 39786607, 2025). "Studies have shown that cancer cells with KRAS mutations are often resistant to certain chemotherapies and targeted therapies." (PMID 41155822, 2025). "A different approach to treat KRAS-mutated cancer cells is by treating cells with a small bifunctional molecule, a proteolysis targeting chimeras (PROTACs), which engages the E3 ubiquitin ligase to KRAS to ubiquitinate KRAS for proteasomal degradation." (PMID 41294676, 2025). "We developed a novel approach combining protein labeling and advanced analysis to compare the interaction partners of normal KRAS with three common cancer-causing mutants (G12C, G12D, and G12V)." (PMID 40427667, 2025). "The rapid evolution in the management of KRAS G12C-mutated cancers necessitates the integration of both biological insights and clinical findings to establish a framework for future therapeutic developments." (PMID 40940900, 2025). "A mutation in the KRAS gene, occurring early in cancer development, is recognized as a driver mutation." (PMID 40771811, 2025). "KRAS mutations are frequently observed in cancers that are closely associated with chronic inflammation, such as pancreatic ductal adenocarcinoma (PDAC), CRC, and lung adenocarcinoma." (PMID 40075661, 2025).
cancer (continued). "The marvelous success of targeting cancers with KRAS-G12C mutations highlighted the potential of targeting KRAS-G12D." (PMID 40430514, 2025). "One cancer had a class 3 mutation (G466V), two atypical KRAS mutations (V14L and D33E), and an NRAS mutation (G12V)." (PMID 39751654, 2025). "KRAS is one of the most frequently mutated oncoprotein, implicated in approximately 23% of all human cancers." (PMID 41294676, 2025). "In summary, this study underscores the evolving role of polymeric nanoparticles in advancing mRNA-based therapies, offering more possibilities for polymer-based CRISPR delivery systems aimed at targeting oncogenic mutations such as KRAS in cancer treatment." (PMID 39687993, 2025). "KRAS is a GTPase that is heavily mutated in many cancers,including% of pancreatic cancers, 40–54% of colorectal cancers,and 27–39% of lung cancers." (PMID 40043012, 2025). "We showed that in addition to regulating cancer cell growth and survival, oncogenic KRAS regulated the transcriptional status of cancer-associated fibroblasts and macrophages in this model." (PMID 39782689, 2025). "The RAS protein family, classified as small GTPases, comprisesHRAS, NRAS, and KRAS, which are among the most commonly mutated genes in human cancers." (PMID 40308511, 2025). "Downregulation of NDUFAF1, a factor for mitochondrial complex I assembly, has been linked to reduced mitochondrial respiration in KRAS-related cancers." (PMID 40567499, 2025). "Despite the critical role of KRAS mutations in cancer, targeting RAS oncoproteins has historically been difficult due to the lack of suitable binding sites on the protein surface." (PMID 41471277, 2025). "This contrasts with Western studies linking specific KRAS mutations to more advanced disease and poorer survival, suggesting potential population-specific differences in cancer behavior." (PMID 41439081, 2025). "KRAS mutations are among the most common oncogenic mutations in human cancers, present in approximately 35% to 49% of CRC cases, with the G12C mutation accounting for about 11% of all KRAS mutations." (PMID 39757310, 2025). "Oncogenic alterations, such as mutations in EGFR and KRAS, along with their downstream signaling pathways, give unique characteristics to cancer cells that shape the TME/TIME." (PMID 40524071, 2025). "KRAS G12C inhibitors represent a significant breakthrough in the treatment of cancers driven by KRAS mutations." (PMID 39806421, 2025). "KRAS mutations are major drivers of human cancers, yet how distinct mutations rewire protein interactions and metabolic pathways to promote tumorigenesis remains poorly understood." (PMID 40427667, 2025). "Clinical studies on cancer therapy using KRAS/G12C inhibitors have revealed KRAS/G12C variants harboring secondary mutations conferring resistance to KRAS/G12C inhibitors." (PMID 40286847, 2025). "These cases were recorded in the cancer registry of the Pathology Department at the National Institute of Oncology/Sabrata between 2019 and 2020 and were referred for further assessment of KRAS/BRAF mutations at the department’s molecular unit." (PMID 41439081, 2025). "A phase I clinical trial has been initiated recently to study the safety and immune response using mutant KRAS peptide to the patients who have familial history of developing cancers or carrier of BRCA2, ATM or PALB2 mutation (NCT05013216)." (PMID 40437549, 2025).
cancer (continued). "KRAS WT amplification is common in patients with gastroesophageal cancers in which it has been shown to act as a unique cancer driver with little overlap to other actionable mutations." (PMID 39711431, 2025). "KRAS mutations are observed in over 20% of human cancers, though the frequency of these mutations varies across different ethnic groups and different anatomical sites of CRC." (PMID 39941797, 2025). "In conclusion, this study highlights the continuous evolution and potential of C14-PEI micelleplexes in advancing CRISPR-Cas9-based therapies for targeted genetic interventions, particularly in addressing mutations such as KRAS in cancer treatment." (PMID 39838780, 2025). "Focusing on the pivotal G12D and G12V mutations prevalent in CRC and PDAC, respectively, our investigation delves into the panoramic trends of cancer‐related genes associated with the KRAS mutational status in these distinct cancers." (PMID 40013338, 2025). "KRAS (Kirsten Rat Sarcoma virus), a well-known proto-oncogene, is frequently mutated and activated in several cancers." (PMID 40830088, 2025). "Their findings revealed that codon 12 and codon 13 mutations in KRAS drive distinct signaling pathways through differential protein expression and phosphorylation, contributing to mutation-specific cancer progression and proliferation." (PMID 41294676, 2025). "TDEs play a crucial role in oncology, particularly in delivering siRNAs targeting oncogenic mutations like KRAS, which addresses critical drivers of cancer progression." (PMID 40149276, 2025). "KRAS mutations enhance the uptake of glucose and its direct intermediates into multiple branching pathways, which supports the malignant behavior of cancer cells." (PMID 39970873, 2025). "This indicates the potential effectiveness of the C14-PEI delivery system in mitigating the aberrant signalling caused by mutant KRAS, thereby affecting cell proliferation and survival pathways involved in cancer progression." (PMID 39838780, 2025). "The isoform of KRAS is the target of most mutations (86%), where distribution and prevalence differ based on different types of cancer." (PMID 40075634, 2025). "The potential benefit of INCB161734 for patients with KRAS G12D-mutated cancers is under investigation in an ongoing phase I clinical trial (NCT06179160), having a 70% phase transition success rate (PTSR) into phase II." (PMID 40597785, 2025). "Mutations in RAS, particularly in its most frequently altered isoform, KRAS, are strongly associated with a variety of human cancers, establishing RAS as one of the most commonly mutated oncogenes." (PMID 41170373, 2025). "RAS gene oncogenic mutations account for about 30% of human cancers such as lung, colon, and pancreatic; KRAS mutations account for 85% of RAS-driven cancer cases." (PMID 40244134, 2025). "RAS proteins are among the most frequent abnormalities in cancer, where KRAS mutations or amplifications are commonly present in solid tumors." (PMID 40885393, 2025). "The specific anticancer effects of RBP on the KRAS G13D mutation were analyzed on the basis of the rate of cell death in different KRAS cancer cell lines." (PMID 40236954, 2025). "Conversely, the cellular resistance to ferroptosis is enhanced by increased oncogenic KRAS; however, inhibitors of ferroptosis have demonstrated efficacy in treating cancers harboring KRAS mutations." (PMID 39875356, 2025). "KRAS neoantigen-specific T-cell receptor (TCR)-adoptive T-cell therapy signifies a considerable advancement in the treatment of KRAS-mutated cancers." (PMID 40075634, 2025). "KRAS mutations have been extensively documented in multiple human cancers, with mutation rates varying significantly across different cancer types." (PMID 41184283, 2025).
cancer (continued). "They discovered that in cancers driven by KRAS mutations, approximately 80% of protein expression changes are regulated at the transcriptional level, alongside other post-transcriptional mechanisms, such as the phosphorylation of ERK proteins." (PMID 40619414, 2025). "The Do‐Cy nanocomplexes offer potential for molecular precision delivery of therapeutic and imaging agents to cancer cells with oncogenic KRAS mutations." (PMID 39951277, 2025). "By mapping these mutation-specific changes, we explain how different KRAS variants promote cancer and identify new targets for precision therapies." (PMID 40427667, 2025). "Activating KRAS mutations are highly relevant to various cancers, and KRAS is the most frequently altered oncogenic protein in solid tumors." (PMID 41309533, 2025). "Many years of research have furthered our understanding of the cellular and biochemical impact of oncogenic KRAS mutations in cancer." (PMID 39412982, 2025). "The small GTPase KRAS is mutated and constitutively active in about 20–25% of all human cancers, in particular pancreatic, lung and colorectal tumours." (PMID 40140597, 2025). "Enrichment analysis revealed KEGG pathways associated with cancer, with KRAS and PIM1 appearing as key nodes." (PMID 40512223, 2025). "The prognosis of patients is significantly impacted by many variables, such as the kind of cancer, histological aspects, and genetic features, including KRAS mutations." (PMID 40756817, 2025). "Some ADAM proteins are involved in the migration and invasion of cancer cells, and their loss can promote the degradation of KRAS." (PMID 40878909, 2025). "Activating mutations in KRAS increasesignaling in several important cellular pathways and are the mostcommon oncogenic drivers in human cancer." (PMID 40043012, 2025). "KRas mutations at codon 61 (Q61) represent the least frequent hotspot for KRas, accounting for only 2% of KRas mutations in all cancers and 5% in PDAC." (PMID 40906088, 2025). "In mice with KRAS mutations, nicotine sped up the development of cancer by promoting cell changes and increasing the occurrence of malignant pancreatic lesions." (PMID 40699746, 2025). "In many cancers, mutations in KRAS impair GTP hydrolysis, resulting in the persistent activation of these pathways, which contributes to immune evasion." (PMID 40333779, 2025). "The KRAS gene is one of the most commonly mutated genes in human cancers, particularly in CRC, LUAD, and PDAC." (PMID 40563429, 2025). "In this study, we attempted to identify shared transcriptional features underlying colon and pancreatic KRAS‐mutant cancers via an integrated ML‐based feature selection (FS) technique and network analysis framework." (PMID 40013338, 2025). "Associations between specific KRAS mutant alleles and race have been discovered in other cancer types." (PMID 39699266, 2025). "KRAS mutations are prevalent in several cancers such as PDAC, NSCLC, and CRC; and the G12, G13, and Q61 positions are frequently mutated hotspots." (PMID 40756996, 2025). "There are other mutations that have relatively lower mutant rates but also have diagnostic, prognostic, or therapeutic influence in KRAS mutant cancer." (PMID 40611261, 2025). "This cluster contained mutations in representative cancer-associated genes such as KRAS, ARID1A, PIK3CA, and FBXW7." (PMID 40679511, 2025). "KRAS mutations are responsible for approximately 25% of all human cancers and about 40% of CRC cases." (PMID 41008802, 2025). "Oncogenic KRAS mutations are among the most prevalent driver alterations in human cancers and in CRC, constitutively activating multiple downstream cellular pathways, including those involved in cell survival and proliferation." (PMID 41300966, 2025). "This aligns with current guidelines recommending anti-angiogenic therapy in right-sided tumors or KRAS-mutated cancers." (PMID 40724549, 2025).
cancer (continued). "The widely recognized oncogene, KRAS, has the maximum mutation rate and correlates with various kinds of cancers that are extremely fatal, such as pancreatic ductal adenocarcinoma (PDAC, 98%), colorectal cancer (CRC, 52%) and lung adenocarcinoma (LAC, 32%)." (PMID 40075634, 2025). "Current clinical trials and research efforts in cancer vaccine development have primarily focused on KRAS and BRAF mutations due to their ability to generate strong neoantigens." (PMID 40429703, 2025). "The high prevalence and poor prognosis associated with KRas G12D mutations in various cancers makes it an attractive target for drug design." (PMID 40837237, 2025). "The sensitivity of KRAS WT–amplified cancer cell lines to the pan-KRAS inhibitors increases with the CN of the KRAS WT allele, with a concomitant increase in KRAS WT mRNA expression." (PMID 39711431, 2025). "Because KRAS mutations underpin both the initiation and progression of cancer, an ideal therapeutic approach would specifically target these mutations without affecting normal tissue." (PMID 40890128, 2025). "Previous studies have highlighted the role of KRAS mutations in enhancing glycolysis and redirecting glycolytic intermediates to biosynthetic pathways essential for cancer cell proliferation." (PMID 40437561, 2025). "In diagnostics, CRISPR‐based platforms like SPEAR offer highly sensitive and rapid detection of critical cancer‐related mutations, such as KRAS, from liquid biopsies, enabling earlier diagnosis and disease monitoring." (PMID 40685330, 2025). "This allowed us to accurately determine the MAFs of somatic mutations and identify clonal proliferation of adenomyotic epithelium with cancer-associated gene mutations as represented by KRAS and PIK3CA mutations using TS." (PMID 40679511, 2025). "TNBC cancer has been associated to driver mutations in the Kirsten Rat Sarcoma Viral Oncogene Homolog (KRAS), and v-Raf murine sarcoma viral oncogene homolog B (BRAF) genes, promoting the synthesis of K-RAS and RAF proteins." (PMID 39936103, 2025). "This work provides crucial insights for developing treatments that specifically counteract the effects of particular KRAS mutations, offering hope for more effective anti-cancer strategies." (PMID 40427667, 2025). "The KRAS oncogene is one of the most frequently mutated genes in human cancer, with mutations detected in approximately 30% of all malignancies." (PMID 40940900, 2025). "It has been long known that KRAS G12 mutations promote glycolysis and anabolic metabolism in cancer cells." (PMID 39883522, 2025). "The dual treatment was able to reduce cancer viability in mutated KRAS cell lines and was more effective than with reovirus alone." (PMID 40526688, 2025). "In KRAS-altered carcinomas and adenocarcinomas, codon 12 is the most frequently mutated, and the G12D mutation is generally the most prevalent." (PMID 40896434, 2025). "Among somatic mutations in KRAS, the most common one is G12D, which is also the most common KRAS mutation in carcinomas." (PMID 40330550, 2025). "Urethane is a tobacco carcinogen that consistently induces a KRAS mutation in mice, initiation of PMLs, and progression to carcinoma." (PMID 40650429, 2025). "The frequency of KRAS mutations in HG adenomas and carcinomas (6/13, 46%) was significantly higher than that in LG adenomas (3/23, 13%)." (PMID 41488735, 2025). "While tumors with a KRAS mutation are more likely to be associated with recurrence and progression to carcinoma, a BRAF mutation is a significant prognostic factor for a favorable course of the disease." (PMID 40564801, 2025). "We further showed that KRAS mutations were commonly identified in HG adenoma and early carcinoma of FAP patients." (PMID 41488735, 2025). "The presence of constantly activated KRAS mutations directs the rearrangement of lipid metabolism and promote the generation of the excessive amount of ROS in cancer cells." (PMID 39501138, 2024).